MDH1 (malate dehydrogenase 1)
Diseases named in the same sentence as MDH1 in open-access papers (continued):
Sharing a sentence is not in itself a finding about the gene and the disease.
cancer (continued). "Additionally, a correlation has been established between MDH1 activity and the aggressiveness of certain cancers, with pancreatic cancer being a notable example." (PMID 40948768, 2025). "Notably, mRNA levels of MDH1 were observed to be markedly elevated in various cancer types, including LUAD, when compared to their healthy counterparts." (PMID 40948768, 2025). "Additionally, by integrating data from GTEx and TCGA, we observed significant overexpression of MDH1 in 19 out of the 33 cancer types analyzed." (PMID 40948768, 2025). "The inhibition of MDH1, a key enzyme in the glutamine catabolic pathway, has been recently reported to sensitize cancer cells to oxidative stress, decreasing cell proliferation and inhibiting tumor growth in vivo, and its targeting is being suggested as a therapeutic approach." (PMID 38132097, 2023). "We found that different cancer cell lines exhibited distinct responses, including sensitivity and insensitivity, to DM-αKG-induced pyroptosis, and that these responses seemed to be unrelated to the expression of MDH1, DR6, caspase-8, and GSDMC." (PMID 34012073, 2021). "Therefore, the dual inhibition of MDH1/2 can be a valuable approach for developing novel anticancer drugs suppressing cancer cell metabolism." (PMID 34452103, 2021). "AC1497 is an effective dual inhibitor of malate dehydrogenase 1 and 2 targeting cancer metabolism." (PMID 34452103, 2021). "In addition, many of the differently regulated proteins are involved in metabolic processes, e.g., TPI or MDH1 in glycolysis and the citric acid cycle, which are both increased in the tear fluid of cancer patients." (PMID 22664934, 2012). "This study provides comprehensive pan-cancer analyses exploring the expression patterns, clinical and pathological correlations, genetic alterations, immunogenomic profiles, single-cell dynamics, alternative splicing signatures, and pharmacological sensitivities related to MDH1." (PMID 40948768, 2025). "Furthermore, robust up-regulation of MDH1, coupled with conformational or post-translational modifications, has been consistently observed in prostate, breast and pancreatic ductal adenocarcinomas, highlighting its pivotal function in rewiring cancer cell metabolism." (PMID 40948768, 2025). "Specifically, the overexpression of MDH1 was significantly correlated with TMB and MSI across multiple cancer types." (PMID 40948768, 2025). "To further investigate the spatial relationship between MDH1 and the macrophage marker CD68, we used a pan-cancer spatial transcriptomics dataset." (PMID 40948768, 2025). "Moreover, MDH1 expression shows complex correlations with various immune cell populations, particularly macrophages, and cohort analysis of both bulk and pan-cancer single-cell immunotherapy data suggest that MDH1 could serve as a predictive marker for immunotherapy responses." (PMID 40948768, 2025). "On the other hand, if additional processes producing NADH in cytoplasm are activated in cancer cells, they will increase the NADH/NAD+ ratio and MDH1 will decrease the additional reductive pressure in the cytoplasm." (PMID 35178152, 2022). "On the other hand, if additional processes producing NADH in the cytoplasm are activated in cancer cells, they will increase the NADH/NAD+ ratio and MDH1 will decrease the additional reductive pressure in the cytoplasm." (PMID 35205619, 2022). "The importance of malate dehydrogenase 1/2, the target of LW1497, in cancer has already been widely reported." (PMID 34829545, 2021). "To explore the clinical implications of MDH1 expression, we conducted a comprehensive analysis to assess its relationship with patient survival metrics, including OS, DSS, DFS, and PFS, across 33 cancer types in the TCGA database." (PMID 40948768, 2025).
cancer (continued). "Nevertheless, a systematic, pan-cancer exploration into the specific roles of MDH1 is notably lacking in current scientific research." (PMID 40948768, 2025). "Additionally, fatty acid metabolism‐related genes, including Acaa2, Mdh2 and Ech1, as well as oxidative phosphorylation‐related genes, such as Sdhc, Cox5a and Mdh1, also upregulated in KAR cancer cells." (PMID 40621620, 2025). "Our research revealed a positive correlation between MDH1 expression and the IC50 of BI-2536, indicating that elevated levels of MDH1 might be involved in fostering BI-2536 resistance in cancer cells." (PMID 40948768, 2025). "Additionally, malate dehydrogenase 1 (MDH1) which is part of this shuttle can activate glycolysis by producing NAD+ in the cytoplasm, as an alternative to LDH as a supplier of NAD+ in cancer cells." (PMID 35178152, 2022). "Notch3 silencing in MCF7 and TFK1 cells results in Mdh1, Idh1 and Ido1 down-representation, as observed in HepG2 and Huh7 HCC cell lines, suggesting that Notch3 regulation of metabolic pathways is a common feature in different human cancer cells." (PMID 30765875, 2019).
tumor (26 papers, 2011 to 2025). "Both TMB and TNB scores exhibited a progressive and significant increase with higher MDH1 expression, suggesting a potential association between MDH1 and enhanced immunogenicity as well as tumor heterogeneity in LUAD." (PMID 40948768, 2025). "Given the heterogeneity of LUAD, we posit that a three-factor classifier combining MDH1 expression, PD-L1 status, and tumor mutational burden may outperform any single marker in predicting immunotherapy response." (PMID 40948768, 2025). "Rescue experiments confirmed that MDH1 mediates the tumor-promoting effects resulting from hsa-miR-513b-5p inhibition in NSCLC cells." (PMID 40626007, 2025). "Subsequent analyses revealed a correlation between MDH1 expression and various clinicopathological parameters, including tumor stage, therapeutic responsiveness, and T and N classifications in LUAD." (PMID 40948768, 2025). "On the epigenetic level, the methylation status of various sites within the MDH1 promoter and gene body showed a strong positive correlation with mRNA expression levels in most tumor samples." (PMID 40948768, 2025). "Hsa_circ_0018909 is significantly upregulated in NSCLC and promotes tumor progression by sponging hsa-miR-513b-5p, thereby indirectly upregulating its downstream target, MDH1." (PMID 40626007, 2025). "A high-level lactate microenvironment reduces tumor cells’ sensitivity to immunotherapy, which is consistent with our conclusion that the high-expression MDH1 group is more sensitive to immunotherapy." (PMID 40948768, 2025). "We used multiplex immunofluorescence to verify the elevated expression of SLC8A1 and MDH1 in immune cell-enriched regions and tumor cell-enriched regions, respectively, both of which were associated with prognosis of NPC." (PMID 37151882, 2023). "The limitation of this study design is that the presence of a tumor must be confirmed to administer Tat-MDH1 to ischemic patients." (PMID 37024665, 2023). "It has been reported that abnormal expression of MDH1 is related to tumor occurrence and progression." (PMID 34044809, 2021). "We found that Notch3-silenced tumours have significant lower levels of Aco1, Idh1 and Mdh1 than control counterparts." (PMID 30765875, 2019). "Additionally, analysis of TCGA data identified a positive correlation between MDH1 expression and tumor stage, as well as the metastatic (M) and nodal (N) classifications in LUAD." (PMID 40948768, 2025). "Moreover, increased expression of MDH1 in tumor cell-enriched regions by transcriptional digital spatial profiling, which were associated with poor prognosis of nasopharyngeal carcinoma." (PMID 40948768, 2025). "Increasing evidence has revealed that alteration in nutrition metabolism can lead to aberrant O-GlcNAcylation, which directly modifies metabolic enzymes such as PGK1, PFK1, G6PD, PKM2 and MDH1 to reprogram metabolic pathways, thereby contributing to tumor growth." (PMID 38778217, 2024). "The large amounts of MDH1 in the serum of STS may also result from production by the stromal cells in the tumor microenvironment." (PMID 38803161, 2024). "The tumor-suppressive effects of methyl 3-(3-(4-(2,4,4-trimethylpentan-2-yl)phenoxy)propanamido)benzoate were investigated and demonstrated that dual inhibition of MDH1 and MDH2 is an effective approach to target tumor metabolism." (PMID 36968582, 2023). "Interestingly, some metabolic enzymes, such as fructose-bisphosphatase 1 (FBP1), pyruvate kinase M2 (PKM2) and malate dehydrogenase 1 (MDH1), act as a tumor suppressor or oncogenic factor alongside their canonical role." (PMID 36419156, 2022). "To assay whether Notch3-mediated regulation of Mdh1, Idh1 and Aco1 protein expression really occurs in primary tumours, we examined protein abundance in Notch3-silenced and control rats after brivanib treatment." (PMID 30765875, 2019).
tumor (continued). "In addition, to determine whether MDH1 is functionally involved in the tumor-suppressive effects of hsa-miR-513b-5p, rescue experiments were conducted by co-transfecting A549 cells with si-MDH1 and a hsa-miR-513b-5p inhibitor." (PMID 40626007, 2025). "MDH1-mediated malate shuttle to maintain NAD and NADH homeostasis to promote tumor cell survival and metastasis in has been extensively studied." (PMID 40963902, 2025). "Few studies have reported the roles of MDH1 and SLC8A1 in NPC or explored the impact of their spatial distribution on the prognosis of tumor patients." (PMID 37151882, 2023). "Besides that, the Mdh1 and Mdh2 proteins that are related to mitochondrial catalytic activity and, together with the Pdhb protein, responsible for the conversion of pyruvate to Acetyl-CoA, showed high concentration in both groups supplemented with leucine, including the tumour-bearing group (L, WL)." (PMID 32668598, 2020). "Our findings are consistent with this tumor-suppressive role and further reveal that miR-513b-5p regulates a novel downstream target, MDH1, in NSCLC—a relationship not previously reported." (PMID 40626007, 2025). "High serum levels of MDH1 and RNH1 and low tumor levels of FABP7 may enable STS to maintain low ROS levels, counteracting the effects of chemoradiotherapy." (PMID 38803161, 2024). "Notably, knockdown of EPRS or LARS did not affect global protein synthesis, while their effects on MAS and tumour progression are exerted, at least in part, through GOT1 or MDH1." (PMID 38769668, 2024). "How increasing the MDH1 activity would benefit the tumor is not explained." (PMID 32916028, 2020). "Consequently, therapeutic strategies targeting MDH1 may simultaneously blunt tumor glycolysis and re-educate TAMs without the need to neutralize lactate itself." (PMID 40948768, 2025).
infection (5 papers, 2019 to 2024). The state of being infected such as from the introduction of a foreign agent such as serum, vaccine, antigenic substance or organism. "Our results confirmed that SCRV infection upregulated the expression of malate-aspartic acid shuttle MDH1/2 and GOT1/2." (PMID 37065159, 2023). "We also found upregulation of key TCA cycle genes, including those encoding for succinate dehydrogenase (Sdhb) and malate dehydrogenase (Mdh1, Mdh2) during infection, which could contribute to reactive oxygen species (ROS) generation." (PMID 37923768, 2023). "ISKNV mainly promoted the expression of MDH1, GOT1, MDH2 and GOT2 in the early stage of infection and further facilitated energy supply, ultimately promoting the proliferation of ISKNV." (PMID 39459874, 2024).
metabolic disorder (3 papers, 2023 to 2024). "MDH1 deficiency can cause severe metabolic disorders, thereby promoting delayed neural development." (PMID 37575300, 2023).
MDH1 also shares sentences with these, for which no sentence is quoted: esophageal squamous cell carcinoma (2 papers); Abdominal obesity (1); cervical cancer (1); cervical squamous cell carcinoma (1); cholangiocarcinoma (1); colon adenocarcinoma (1); dementia with Lewy bodies (1); endocervical adenocarcinoma (1); fatal familial insomnia (1); head and neck squamous cell carcinoma (1); Huntington disease (1); leukemia (1); metastatic melanoma (1); ovarian carcinoma (1); prostate carcinoma (1); rectal cancer (1); retinitis pigmentosa (1); retinopathy of prematurity (1); stomach adenocarcinoma (1); thyroid carcinoma (1); uterine corpus endometrial carcinoma (1); x-linked sideroblastic anemia (1).